LEP (leptin)
Diseases named in the same sentence as LEP in open-access papers (continued):
Sharing a sentence is not in itself a finding about the gene and the disease.
metabolic disorders (continued). "Therefore, the aim of this review was to summarize the current knowledge of the epigenetic regulation of leptin as well as the leptin-induced epigenetic modifications in metabolic disorders and associated phenomena." (PMID 31408957, 2019). "Thus, in utero memorization mechanisms contribute to increased risk of metabolic diseases in later life, and this occurs at least in early life as for leptin’s epigenetic regulation." (PMID 31408957, 2019). "The collected data indicated that the deregulation of leptin expression and secretion that occurs during the course of metabolic diseases is underlain by a variation in the level of promoter methylation, the occurrence of histone modifications, along with miRNA interference." (PMID 31408957, 2019). "Leptin and adiponectin demonstrated the expected associations with metabolic disorders." (PMID 29759068, 2018). "The use of microorganisms with low and middle inflammatory properties and ability to modulate leptin levels could be a strategy for the treatment of some metabolic diseases associated with immune abnormalities." (PMID 28348560, 2017). "The use of microorganisms with low and medium inflammatory properties and ability to modulate leptin levels could be a strategy for the treatment of some metabolic diseases associated with dysregulation of immune response." (PMID 28348560, 2017). "We then tested whether isorhamnetin could ameliorate metabolic disorders in leptin deficient ob/ob mice." (PMID 26775807, 2016). "Metabolic disorders causing insulin resistance syndrome can be seen in gestational hypertension disorders including increased levels of plasminogen activator inhibitor −1, leptin, and tumor necrosis factor alpha." (PMID 24812607, 2014). "Yet, more valuable information regarding the potential of leptin to serve as a diagnostic and prognostic marker might be obtained from the adiponectin/leptin ratio, which is an excellent marker for metabolic diseases, and negatively correlates with measures of low-grade inflammation." (PMID 37238973, 2023). "Thus, dietary interventions and exercise protocols designed to reduce plasma leptin levels may improve not only metabolic disorders associated with hyperleptinemia, but cognitive function as well." (PMID 35527735, 2022). "Leptin may be a critical link associated with coexisting metabolic disorders." (PMID 34671315, 2021). "We further examine the underlying molecular mechanisms and signaling pathways involved, aiming to clarify the context-dependent effects of leptin and identify key knowledge gaps to guide future research in adipose tissue biology and metabolic disease." (PMID 42278307, 2026). "This approach enables a more accurate isolation of leptin’s effects from potential confounding factors related to pharmacological treatments, comorbidities, or established metabolic disorders." (PMID 40507178, 2025). "This developmental plasticity represents both a window of vulnerability, where adverse nutritional or hormonal cues can program future metabolic disease by impairing hypothalamic responses to insulin and leptin, and a window of opportunity for intervention." (PMID 41409607, 2025). "Proteomic analysis illustrated that the expression of certain proteins including AGRP, LEP and SORT1 associated with metabolic diseases decreased following THD treatment." (PMID 40242450, 2025). "Leptin physiology in children is crucial for diagnosing and managing pediatric endocrine and metabolic disorders." (PMID 40152811, 2025). "Higher BMI is explained through multiple pathways, from systemic inflammation, reduced muscle tone, lower leptin levels, lower resting energy expenditure, concomitant metabolic diseases, slow metabolism of medications, and poor dietary habits." (PMID 40428048, 2025). "Numerous adipokines, including adiponectin, leptin, and resistin, are secreted by adipose cells and can result in metabolic disorders and systemic inflammation." (PMID 40941124, 2025).
metabolic disorders (continued). "PTP1B is recognized for its adverse regulating influence on leptin and insulin signaling, leading to substantial implications for the development of metabolic diseases." (PMID 40341376, 2025). "Understanding the nuances of leptin physiology in children can be crucial for diagnosing and managing pediatric endocrine and metabolic disorders." (PMID 40152811, 2025). "Exogenous leptin treatment has also shown benefits for metabolic disease in patients with PL, though these effects can be variable, with certain subgroups showing more pronounced improvements." (PMID 40520449, 2025). "The dysregulation of adipocytokines, such as resistin, leptin, and especially adiponectin, plays a pivotal role in the pathophysiology of metabolic diseases." (PMID 38756259, 2024). "The relationship between different genetic variants and BMI in KOA patients has been shown, among which there are a large number of genes associated with metabolic disorders (FTO, ADIPOQ, LEP, SREBP2) and other genes (GDF5, TGFB1, etc.)." (PMID 38424630, 2024). "The adiponectin‐to‐leptin ratio (A/L ratio) has been appointed as a potential marker of adipose tissue dysfunction and metabolic disorders, with a higher A/L ratio suggesting a more favourable metabolic profile." (PMID 38632706, 2024). "Plasma leptin is related to insulin resistance, inflammation and thus participate in the long-term metabolic diseases regulation." (PMID 39256355, 2024). "Adipocytokines, particularly resistin, leptin, and adiponectin, play a crucial role in the onset of obesity and related metabolic diseases." (PMID 38756259, 2024). "Disruptions in leptin and adiponectin signaling can lead to dysregulation of lipid metabolism and contribute to the development of metabolic disorders." (PMID 37685080, 2023). "We found that the greater the reduction in asprosin level, the lower the level of risk factors for metabolic disorders: e.g., AIP and the leptin/adiponectin index." (PMID 37629307, 2023). "Most of the PAKs that researchers think to be involved with the metabolic diseases are leptin, TNFα, IL-6 and resistin." (PMID 37014444, 2023). "Circulating levels of chemerin, leptin, and galectin-3 are commonly elevated, while serum adiponectin levels are reduced in the obese and all of those changes are related to metabolic diseases." (PMID 37238973, 2023). "Using Tmem135 mutant mice, we also validated the protective effect of increased peroxisomes and peroxisomal beta-oxidation on the metabolic disease phenotypes of leptin mutant mice which has been observed in previous studies." (PMID 36599953, 2023). "Studies have reported that leptin is a key regulator of HCC development and ectopic serum leptin levels are regarded as a hallmark of metabolic disorders leading to HCC." (PMID 37266440, 2023). "Excess adipose tissue increases the production of pro-inflammatory factors such as leptin, tumor necrosis factor-α, interleukin-6, and resistin which contribute to the development of various metabolic diseases." (PMID 35287586, 2022). "Olanzapine increases leptin levels, food intake, and weight, induces oxidative stress, decreases the levels of AMPK and P-AMPK proteins in liver tissue, and causes metabolic disorders." (PMID 35655598, 2022). "Leptin regulates food intake and energy expenditure, whereas adiponectin regulates lipid and glucose metabolism and can suppress the development of metabolic disorders." (PMID 35276805, 2022). "Understanding how leptin modulates glucose homeostasis is therefore an important goal in trying to treat metabolic disorders." (PMID 35454388, 2022). "The effects of exercise on circulating leptin levels are summarized, and the results of clinical application of leptin to metabolic disease and neurologic dysfunction are reviewed." (PMID 35527735, 2022). "Meanwhile, other related metabolic disorders, specifically including the leptin and total TC in the plasma, were markedly upregulated in HFD‐fed mice (p < .01, versus Con)." (PMID 35154697, 2022).
metabolic disorders (continued). "It has been suggested that the leptin-to-adipokine (Lep/Adpn) ratio is an indicator of metabolic disorders." (PMID 35406070, 2022). "Numerous studies based on cellular and mouse models have shown that QUE has therapeutic effects on metabolic disorders through a variety of mechanisms, such as increasing adiponectin, decreasing leptin, and antioxidant activity." (PMID 36274842, 2022). "Taken together, as an adipokine, leptin is considered not only a marker of adipose expansion, but also the driving force of metabolic disorders by targeting diverse tissues in obesity." (PMID 35896788, 2022). "Leptin plays several roles in the regulation of pregnancy-related functions, while metabolic disorders and dynamic imbalances related to leptin during pregnancy play a decisive role in the occurrence and development of PE." (PMID 36685185, 2022). "The presence of metabolic disorders is also represented by an inverse relationship between leptin and adiponectin concentrations in obese patients." (PMID 35386232, 2022). "This dysfunction promotes metabolic disorders via a mild, chronic inflammation which is characterized by an increased expression of pro-inflammatory factors such as leptin, TNFα, IL6 or monocyte chemoattractant protein-1 (MCP-1 — also known as CCL2)." (PMID 34646852, 2021). "The identification of these factors and the experimental evidences of direct interaction between phosphor-STAT3 and its target gene would hopefully illuminate our way to overcome leptin resistance and metabolic disorders." (PMID 33849593, 2021). "It is now clear that leptin has multiple relevant roles in the body, and many research efforts are driven to elucidate the intricate network among, leptin metabolic disorders, inflammatory diseases, and the immune system." (PMID 33673730, 2021). "It has been indicated that the levels of leptin and leptin receptor and also LEP rs7799039 and LEPR rs1137101 polymorphisms are associated with metabolic disorders." (PMID 34407095, 2021). "Leptin is produced by peripheral adipose tissue and plays a role in the CNS, which cannot be ignored when investigating the development of metabolic diseases." (PMID 33763034, 2021). "This process occurs at low rates under basal conditions, but it can be induced by diverse types of stress such as starvation, hypoxia, metabolic disorders or in response to hormones, including leptin." (PMID 33763424, 2021). "Leptin is a hormone that regulates energy balance and food intake, as well as glucose homeostasis, therefore making leptin a central regular of metabolic disease." (PMID 32816039, 2020). "In support of this view, multiple independent investigations have recognized the possibility of the level of serum leptin in adulthood as a predictor of metabolic diseases development." (PMID 33114326, 2020). "The increased risk is mediated through sex-specific genetic alterations in downstream molecules of leptin signaling, which impairs hypothalamic leptin signaling prior to the development of metabolic diseases, and results in the onset of metabolic diseases." (PMID 33114326, 2020). "Some metabolic disorders can generate a leptin increase and a reduction of vitamins that have been shown to gastric intestinal metaplasia in mice and the modification of human microbiota." (PMID 33182527, 2020). "Metabolic disorder was evaluated by measuring the fasting body weight, glycemia and C-peptide and leptin." (PMID 32256672, 2020). "In summary, the evidence suggests that leptin is both a target and a mediator of epigenetic changes that develop in numerous tissues during metabolic disorders." (PMID 31408957, 2019). "Consistent with mice studies, administration of recombinant leptin effectively improved metabolic disorders in patients with lipodystrophy or congenital leptin deficiency." (PMID 31736870, 2019).
metabolic disorders (continued). "Understanding the role of E2 and leptin in regulating gut microbiota will provide important insights into hormone-dependent metabolic disorders in women." (PMID 31882890, 2019). "Dysregulation of leptin and kisspeptin signaling as anorexigenic agents is believed to be the connection between metabolic disorders and altered reproductive function." (PMID 31871451, 2019). "This clinical piece of evidence is consistent with our findings and it would indicate that because of ongoing Jak2 inhibition, leptin cannot exert its retroactive control on FI and BW, which would therefore favor BW gain and metabolic diseases over time." (PMID 29867515, 2018). "Among the numerous adipokines deprived from adipose tissue, adiponectin and leptin are crucial signal link between adiposity and metabolic disorders." (PMID 29020116, 2017). "It is well known that adult patients with GHD show a tendency towards metabolic disorders (higher body mass, unfavourable lipids, and increased leptin and insulin concentrations) and that they return to normal levels following GH treatment." (PMID 28596789, 2017). "Pro-inflammatory factors for metabolic disorders such as serum insulin, leptin, and resistin were positively correlated with serum stearic acid and γ-linolenic acid simultaneously." (PMID 28317846, 2017). "Despite great potential of the approach based on the restoration of the brain leptin signaling in metabolic disorders, currently leptin is used to a limited extent in clinic to treat and prevent MS and T2DM." (PMID 28031898, 2015). "Dissecting the regulation of long-term glucose homeostasis via pathways involving both insulin and leptin would be critical to understanding progression of metabolic diseases." (PMID 26540285, 2015). "Human LEP locates on chromosome 7q31.3, and its translational product is leptin, which plays a decisive role in the regulation of human appetite and results in severe metabolic disorders." (PMID 24707501, 2014). "AMPK is activated in response to several pharmacological agents and some hormones, such as metformin, statins, resveratrol, 5-aminoimidazole-4-carboxamide-1-β-d- ribofuranoside, adiponectin and leptin, exerting its beneficial effects on metabolic disorders." (PMID 25365359, 2014). "It is also known that visceral adipose percentage, insulin levels, and leptin levels are higher in persons with more severe metabolic disorder." (PMID 22587351, 2012). "Pharmacological leptin has so far been given to patients for peripheral metabolic disorders and to modulate behaviours and endocrine pathways in the hypothalamus." (PMID 22013440, 2011). "In fact, changing levels of leptin act as an adiposity marker that alerts of metabolic disorders, usually related to alterations in food intake, that may translate to growth impairment." (PMID 40003042, 2025). "Several factors appear to be related to the hepatic and/or metabolic response to exogenous leptin treatment, including the severity of metabolic disease at baseline, levels of triglycerides and triglyceride-rich apolipoproteins, baseline leptin levels, and changes in IGF-1 levels." (PMID 40520449, 2025). "The relationships between adiponectin, leptin, visfatin, and traditional indicators of metabolic diseases suggest that these adipokines could serve as additional markers of IR." (PMID 40289929, 2025). "Elevated levels of leptin and resistin may decrease inflammatory response and metabolic disorders, indicating how periodontal treatment helps regulate systemic metabolism." (PMID 41244040, 2025). "Another consequence of metabolic disorders is the disruption of the endocrine system, which leads to hormonal changes, such as elevated insulin and leptin levels, insulin resistance in peripheral tissues, and decreased adiponectin, all of which contribute to reduced fatty acid oxidation." (PMID 39839806, 2024). "However, the contribution of leptin to the development of other metabolic disorders in PCOS appears inconsistent." (PMID 38826091, 2024).
metabolic disorders (continued). "Insulin and leptin were reliable biomarker of glycolipid metabolism disorders." (PMID 38962449, 2024). "This inflammatory response disrupts insulin and leptin signaling and affects neuronal function through the accumulation and activation of astrocytes—both important contributors to the onset and progression of various metabolic diseases." (PMID 39590331, 2024). "Metabolic diseases have been postulated to be concomitant in patients with LS/LA and may lend insight into leptin dysregulation." (PMID 39677150, 2024). "Metabolic markers such as leptin and adiponectin could serve as alternative indicators of the effect of ephedra on weight reduction or the treatment of metabolic disorders." (PMID 39539620, 2024). "Several studies have found that variants in certain genes (especially LEP, HTR2C, and SREBF2) may make patients taking clozapine genetically susceptible to metabolic disorders." (PMID 37744899, 2023). "In our report, we confirmed in a homogeneous population of non-chemorefractory patients, the association between leptin-mediated overt metabolic disorders, blood pro-inflammatory cytokine profile and responsiveness to maintenance IO." (PMID 37668709, 2023). "Maternal metabolic disorders have discernible effects on the composition of immune-related components in breast milk, such as immunoglobulins, lactoferrin, leptin, ghrelin, adiponectin, C-reactive protein, growth factors, extracellular vesicles, and lymphocytes." (PMID 38140275, 2023). "Furthermore, this study identified elevated FPG as a significant predictor of increased serum leptin levels in patients with CKD and a risk factor for metabolic diseases." (PMID 36698704, 2023). "Intracerebroventricular (ICV) administration of leptin into ob/ob mice or re-expression of leptin receptor in the CNS of db/db mice can fully reverse the corresponding metabolic disorders, highlighting the involvement of the CNS in mediating the effects of leptin." (PMID 38027481, 2023). "Reasonable manipulation of leptin could be a possibility in therapy for metabolic diseases where hyperleptinemia is present." (PMID 37108229, 2023). "Leptin and adiponectin are involved in pancreatic physiology as well as human pancreatic adipocytes release adipokines; thus, dysfunction of this adipoinsular feedback loop results in metabolic disorders." (PMID 37444627, 2023). "Although abnormal adipose growth and metabolic disease were not seen in KI mice, the low plasma leptin concentration seen in human adipose overgrowth associated with MFN2 mutations was replicated." (PMID 36722855, 2023). "However, a study conducted in Unite State found that leptin level significantly elevated in both normal weight and overweight or obese people with metabolic abnormalities, which can be used to determine metabolic disorders." (PMID 37711898, 2023). "However, several studies have found that long-term feeding of high concentrate diets can induce metabolic disorders which are related to abnormal hormones levels, including cortisol, leptin, and insulin." (PMID 34991199, 2022). "Therefore, high leptin levels are closely related to metabolic diseases in which excessive adipocytes can increase leptin levels." (PMID 36698957, 2022). "Moreover, chronic inflammation (as assessed by different biomarkers such as proinflammatory adipokine, leptin, and/or proinflammatory cytokines IL-6 and IL-1β) has been described to play a crucial role in the development of metabolic disease." (PMID 36006128, 2022). "In addition to the known link between leptin and metabolic disorders and diseases, leptin also affects the cardiovascular system." (PMID 36698957, 2022). "(2017) have shown that lowering adiponectin and leptin may contribute to the increase of oxidative stress and the development of metabolic disorders." (PMID 36479221, 2022).